IDH1 (isocitrate dehydrogenase (NADP(+)) 1)
Diseases named in the same sentence as IDH1 in open-access papers (continued):
Sharing a sentence is not in itself a finding about the gene and the disease.
oligodendroglioma (continued). "To interrogate the spatial intratumoral heterogeneity of HGG, we selected 3 IDH wild-type WHO grade 4 GBM (GBM −1 to 3) and 3 IDH1-mutant grade 3–4 oligodendroglioma (O-1) and astrocytoma (A-2, A-3) samples for spatial whole transcriptome analysis." (PMID 38077210, 2023). "Immunohistochemical workup of most oligodendrogliomas shows immunoreactivity for IDH1 R132H and retention of normal nuclear ATRX." (PMID 37239289, 2023). "One important case report described a patient with refractory GRE due to an IDH1mut oligodendroglioma in which the IDH1 inhibitor ivosidenib was effective in reducing the patient’s seizure frequency." (PMID 38026690, 2023). "In oligodendrogliomas with T2FMM, IDH1‐mutations or specific differentially expressed genes were not identified." (PMID 37246729, 2023). "The work published by Tirosh I. and colleagues documented different gene expression profile signatures of 4347 single cells on oligodendrogliomas, showing the classical IDH1/IDH2 dualism." (PMID 37510235, 2023). "All oligodendroglioma cases were immunopositive for IDH1-R132H immunostains, the three cases of central neurocytoma were immunopositive for synaptophysin, and the three cases of ependymoma showed at least focal dot-like cytoplasmic immunopositivity for EMA." (PMID 35885538, 2022). "For instance, in IDH1 or IDH2 mutant human oligodendrogliomas, distinct CNV sub-clones displayed similar cellular hierarchies, suggesting that the cell states were primarily dictated by developmental programs." (PMID 34405376, 2022). "The molecular background of oligodendrogliomas WHO grades II and III can be confirmed by demonstrating combined IDH1/2 mutations and chromosomal losses on 1p and 19q." (PMID 35018523, 2022). "In our cohort of 22 patients, there was relatively equal representation of IDH1/2 mutant oligodendroglioma and diffuse astrocytoma." (PMID 35448183, 2022). "The discovery of mutations in the IDH1 and IDH2 genes in astrocytic and oligodendroglial tumours has led to a biomarker-driven classification, forming an integrated diagnosis composed of the histological appearance and the molecular profile." (PMID 35029738, 2022). "The 2016 WHO guidelines recommend that oligodendrogliomas should be diagnosed by morphology, IDH1 mutant and 1p/19q codeletion status." (PMID 34458259, 2021). "Thirty-five out of 39 oligodendroglioma cases that were positive for IDH1-R132H and ATRX, and reduced H3K27me3, exhibited 1p/19q codeletion." (PMID 34020723, 2021). "One unexpected finding is the highest expression of IDH1 enzyme in oligodendrocyte-like cells than in astrocyte-like cells in oligodendroglioma." (PMID 33925547, 2021). "The case of RAS-mutant anaplastic oligodendroglioma showed IDH1 and TERT promoter mutations, which are known to be detected in almost all oligodendrogliomas." (PMID 34525976, 2021). "Our prediction models indicate the clinical utility of H3K27me3 IHC for the prediction of IDH1-R132H Mut 1p/19q codeleted oligodendroglioma along with IDH1-R132H and ATRX IHC." (PMID 34020723, 2021). "Mutations in IDH1, or less frequently IDH2, define two major classes of malignant gliomas: astrocytoma (IDH-A) and oligodendroglioma (IDH-O)." (PMID 34948008, 2021). "All 45 cases of oligodendroglioma showing 1p/19q codeletion also presented with an IDH gene mutation (40/45 IDH1-R132H, 1/45 IDH1-R132L, 4/45 IDH2)." (PMID 34020723, 2021). "In the oligodendroglioma, we found that >95% of ETNPPL+ cells also expressed the mutated form of IDH1 R132H." (PMID 32218467, 2020). "IDH1/2 mutations have been estimated to occur in 54–100% of diffuse astrocytomas (WHO II), 66.1% of anaplastic astrocytomas (WHO III), and 64–93% of oligodendrogliomas (WHO II and III) cases." (PMID 32120790, 2020). "Secondary xenografts formed in 3 of 9 mice that continued to exhibit oligodendroglioma histology, although with slightly less infiltration, and continued to express IDH1 R132H." (PMID 32904945, 2020).
oligodendroglioma (continued). "Oligodendroglioma (ODG) are CNS resistant tumors characterized by their unique molecular signature, namely a combined deletion of 1p and 19q simultaneously to an IDH1/2 mutation." (PMID 32854646, 2020). "In IDH1 mutant oligodendroglioma patients, the most frequent immune targets on CD8+ TILs were A2aR and PD-1; GIMs also showed high expression of A2aR." (PMID 32721947, 2020). "Of particular note, IDH2-mutant tumors were localized within the expression space of oligodendrogliomas, indicating a distinct expression profile from that of IDH1-mutant oligodendrogliomas." (PMID 32732999, 2020). "The tumor was removed en bloc and histopathological examination showed oligodendroglioma WHO grade II with densely packed IDH1-labeled tumor cells located mainly in the grey matter." (PMID 30109401, 2019). "TCF12 mutations occurred only among oligodendrogliomas 1p19q codeleted with TERT promoter mutations and with IDH1 or IDH2 mutations (particularly frequent among IDH2-mutated tumors)." (PMID 30279357, 2018). "We also noted that the medial frontal cortex was a location specific for IDH1/2-mutant with TERT promoter mutant oligodendrogliomas." (PMID 30082856, 2018). "It was also described that mutant IDH1 enzyme was correlated with high mitochondrial density and increased mitochondrial activity in oligodendroglioma cell line xenografts in vivo." (PMID 30404651, 2018). "Oligodendroglioma as a histology is highly enriched for IDH1/2 and 1p/19q co-deleted tumors (117/174, or ~67% within TCGA) and it is therefore likely that the analysis using only tumors classified as oligodendroglioma captured most of this molecular subtype." (PMID 29743610, 2018). "Three types of molecular subtypes were identified: IDH1/2-mutant (IDH-mutant astrocytomas), IDH1/2-mutant with TERT promoter mutation (IDH, TERT co-mutated oligodendrogliomas), and IDH-wild type (IDH-wildtype astrocytomas)." (PMID 30082856, 2018). "For example, 1p/19q co-deletion, IDH1/2 and TERT promoter mutation are oligodendroglioma defining alterations." (PMID 28388591, 2017). "In the oligodendroglioma case, which featured TERT mutation, IDH1 mutation, and 1p19q co-deletion, high levels of tracer uptake were found in both PET studies (Case 4)." (PMID 28660218, 2017). "IDH1-R132H immounohistochemistry has also been shown to be effective in separating out oligodendrogliomas from several other similar entities, such as central neurocytomas, tanycytic ependymomas, and pilocytic astrocytomas." (PMID 26858939, 2016). "ATRX retention in IDH1/2 mutant tumors was strongly associated with LOH 1p/19q and oligodendroglioma histology (p < 0.0001)." (PMID 27311324, 2016). "Our findings mirror this classification, with 1p/19q deletions mostly confined to oligodendrogliomas with and IDH1 mutation or G-CIMP signature, and EGFR amplification observed mostly in IDH1 wild type GII/III s and GBMs." (PMID 24614622, 2014). "Further investigations have shown that mutations in IDH1 and IDH2 are present in high proportions of grade II and III astrocytic and oligodendroglial tumours (72–100%) along with secondary GBMs (85%), but are largely absent in primary GBMs (5%)." (PMID 25147764, 2014). "Grade II-III oligodendrogliomas have frequent co-occurring mutations in the TERT promoter and IDH1/2." (PMID 24722048, 2014).
oligodendroglioma (continued). "Oligodendrogliomas were almost exclusively TERT promoter and IDH1/2 mutated (79.3%, 69/87), but a fraction, 17.2% (15/87) harbored mutations in IDH1/2 alone." (PMID 24722048, 2014). "Tumors harboring mutations typically seen in oligodendroglioma (both TERT promoter and IDH1/2 mutation) had a more favorable prognosis (median 125.2 months)." (PMID 24722048, 2014). "We analyzed a cohort of 17 oligodendroglial tumor samples, consisting of nine cases diagnosed as oligodendroglioma (O) and eight as oligoastrocytoma (OA) for copy number variations (CNV); CIC, FUBP1 and IDH1/IDH2 mutations; and gene expression changes." (PMID 24086756, 2013). "We have successfully established and serially passaged a grade III oligodendroglioma xenograft with the hallmark chromosome 1p and 19q losses and mutations including FUBP1, CIC, and IDH1 (R132H)." (PMID 23527265, 2013). "We here present a detailed histologic and metabolic characterization of the E478 IDH1-R132H mutant oligodendroglioma xenograft line, the development of which has been described before." (PMID 24252742, 2013). "One oligodendroglioma grade 2 was IDH1 negative, one oligodendroglioma grade 2 not tested, and the remaining tumours were IDH1 mutated." (PMID 40703546, 2025). "Histology revealed a WHO Grade 3 oligodendroglioma, IDH1 positive, 1p/19q co-deleted." (PMID 39239149, 2024). "Similarly, a patient-derived oligodendroglioma xenograft model showed an increased mitochondrial activity compared to IDH1-wildtype xenografts." (PMID 37108511, 2023). "H3K27me3 has reduced in 90% (36/40) of IDH1-R132H Mut oligodendrogliomas." (PMID 34020723, 2021). "However, all IDH2 Mut oligodendrogliomas showed retained H3K27me3 staining, indicating a differential methylation status between IDH1 and IDH2 Mut groups (P ≤ 0.05)." (PMID 34020723, 2021). "This case report supports possible distinct molecular pathogenesis in supratentorial and infratentorial oligodendrogliomas and raises questions about the role of different IDH1 mutant isoforms in explaining treatment resistance to different chemotherapy regimens." (PMID 34587990, 2021). "In contrast, loss of H3K27me3 was never seen in IDH1-R132L or IDH2-mutated 1p/19q codeleted oligodendrogliomas." (PMID 34020723, 2021). "Finally, we observed a higher level of APOE, BMP4, KCNN3/SK3, and CRYAB proteins in astrocyte-like cells, whereas the IDH1 enzyme appears to be more expressed in oligodendrocyte-like cells in oligodendroglioma." (PMID 33925547, 2021). "However, in IDH1 wild-type cases, pediatric oligodendrogliomas most frequently harbor alterations in FGFR1 including TKD-duplications or SNVs or BRAF p.V600E." (PMID 32164789, 2020). "In the most recent WHO iteration, both diffuse astrocytoma and oligodendroglioma have been split based on the presence or absence of IDH1 mutations, in addition to 1p/19q co-deletion for the latter." (PMID 32164789, 2020).
oligodendroglioma (continued). "In contrast, luciferase-modified oligodendroglioma PDCs (SF10417 PDC-LUC GNS) yielded infiltrative tumors in 4 of 9 mice and the tumors exhibited oligodendroglioma histologic features and maintained IDH1 R132H expression as measured by IHC on formalin-fixed, paraffin-embedded xenograft tissue." (PMID 32904945, 2020). "By using the antibody against IDH1-mutated protein as a marker for tumor cells, we confirm previously established correlations between MET and cell density, and extend these findings to a correlation between MET and tumor cell density in oligodendrogliomas." (PMID 30109401, 2019). "In our study, IDH1 (R132H) expression was detected in 23 (92%) oligodendrogliomas cases, 12 (80%) anaplastic oligodendrogliomas cases, 1 (100%) oligodendrogliomas NOS case, 12 (85.7%) A cases, 3 (75%) anaplastic astrocytoma cases, and 1 (100%) anaplastic oligoastrocytomas case." (PMID 30592195, 2019). "Therefore, mutations other than IDH1 and 1p/19q-codeletion including TERT promoter mutation appear to be later events in oligodendroglioma oncogenesis." (PMID 28270234, 2017). "Both IDH1 mutant, 1p/19q co-deleted tumors showed a proneural gene expression signature, and, therefore, displayed genetic alterations resembling those seen in oligodendrogliomas." (PMID 26757882, 2016). "Furthermore, the recent identification of IDH1, CIC and TERT mutations will lead to new models that should give more insights into the mechanisms of oligodendroglioma genesis." (PMID 25008045, 2014). "In oligodendrogliomas, TERT promoter and IDH1/2 mutations co-occurred in 79% of cases." (PMID 24722048, 2014). "These three models derived from anaplastic oligodendrogliomas but did not harbor the typical alterations, namely the 1p/19q co-deletion and the IDH1 mutation." (PMID 23874590, 2013). "Three out of four oligodendrogliomas and one oligoastrocytoma were all mutated at codon 132 of IDH1 whereas one oligodendroglioma did not harbor mutations at the canonical codons 132 or 172 of IDH1 or IDH2." (PMID 24349039, 2013). "Since all four oligodendroglioma lines used in the study expressed wild-type IDH1/2, it is possible that cells harboring IDH mutations cannot be propagated in vitro because cell culture selects for the more aggressive wild-type IDH1/2 cells." (PMID 24278309, 2013). "The tumors presented IDH1 (R132H) mutations detected by IHC and Sanger sequencing (performed for the primary tumor only) and showed nuclear immunopositivity of ATRX in consistence with the 2021 WHO classification criteria for the diagnosis of oligodendroglioma, IDH-mutant and 1p/19q-codeleted." (PMID 36739454, 2023). "Immunohistochemical analysis for H3K27me3, ATRX, and IDH1-R132H revealed that diffuse gliomas with a loss of nuclear H3K27me3 staining, retained ATRX staining, and IDH1-R132H positivity can be predicted as 1p/19q codeleted oligodendrogliomas with a probability score of 0.9835." (PMID 34020723, 2021). "The number of non-canonical IDH1/2 mutated 1p/19q codeleted oligodendrogliomas is small (n = 5)." (PMID 34020723, 2021). "Tumors with the morphology of oligodendroglioma or diffuse astrocytoma in the pediatric age group often do not have IDH1 mutations and/or 1p/19q co-deletion and are therefore considered oligodendroglioma, NEC or, of even greater concern, diffuse astrocytoma, IDH-wildtype." (PMID 32164789, 2020). "This novel classification system incorporates mutations in the isocitrate deshydrogenase 1 and 2 genes (IDH1 and IDH2) and the whole-arm chromosomal loss of 1p and 19q (1p/19q-codeletion), which are both required to be present for confirming the diagnosis of oligodendroglioma." (PMID 30193580, 2018). "Tumors with loss of ATRX expression and IDH1/2 mutations can be reliably classified as diffuse astrocytomas while IDH1/2 mutant tumors with retained ATRX expression should undergo testing for 1p/19q co-deletion to help differentiate between a diffuse astrocytoma and oligodendroglioma." (PMID 29359122, 2017).
oligodendroglioma (continued). "By contrast, SSTR2 expression was associated with IDH1 mutation (P = 0.007), oligodendroglioma component (P = 0.010), lower grade (P = 0.005), absence of EGFR amplification (P = 0.021), and longer progression-free survival (HR 0.161, CI 0.037 to 0.704, P = 0.015)." (PMID 25977882, 2015). "It is possible that the mutations in IDH1 and CIC may in fact be moderately deleterious and reduce clonogenicity but may provide other timely survival advantages under certain conditions during oligodendroglioma disease progression." (PMID 25277207, 2014). "The pathology, immunohistochemistry, and gene sequencing analyses revealed an IDH1 R132H mutant, 1p19q co-deleted, WHO grade 2 oligodendroglioma." (PMID 38957232, 2024). "Additionally, the presence of an IDH1/2 mutation in combination with 1p19q co-deletion became diagnostic of oligodendroglioma, irrespective of whether the neoplasm demonstrated astrocytic or oligodendroglial morphologic features." (PMID 38893099, 2024). "For oligodendroglioma, ATR inhibitors, IDH1 inhibitors, and pembrolizumab were recommended (n = 1 for each)." (PMID 35626060, 2022). "In addition, a chromosome 1p/19q co-deletion is shown in 50–80% of oligodendrogliomas, while 1p/19q deletion is not observed in liponeurocytomas and also oligodendrogliomas show a high frequency of isocitrate dehydrogenase 1 (IDH1 R132H) mutation in addition to 1p/19q co-deletion." (PMID 33964714, 2021). "Moreover, it is unknown whether IDH1-R132H and non-canonical IDH1/2-mutated oligodendrogliomas have different prognostic and therapeutic characteristics." (PMID 34020723, 2021). "Third row (panel γ) shows recurrence of a WHO III° oligodendroglioma (MGMT−, IDH1−), originally categorised as treatment-related effect." (PMID 31601829, 2019). "Fourth row (panel δ) presents a patient with WHO III° oligodendroglioma (MGMT−, IDH1+, LOH1p/19q+), which was classified as post-treatment related effect." (PMID 31601829, 2019). "First row (panel α) demonstrates a patient with a treated WHO III° oligodendroglioma (MGMT+, IDH1+, LOH1p/19q+), originally classified as relapse." (PMID 31601829, 2019). "We next measured ACLY and pACLY levels in 1p19q co-deleted oligodendroglioma patient samples with known CIC and IDH1 status." (PMID 25277207, 2014). "We analyzed 17 oligodendrogliomas and oligoastrocytomas by applying a comprehensive approach consisting of RNA expression analysis, DNA sequencing of CIC, FUBP1, IDH1/2, and array CGH." (PMID 24086756, 2013). "Vorasidenib, a dual IDH1/2 inhibitor, has demonstrated significant progression-free survival in the phase III INDIGO trial and, as of August 2024, holds FDA approval for patients aged 12 years and older with grade 2 astrocytoma or oligodendroglioma." (PMID 41375081, 2025). "Prognostic features in non-TCGA IDH1/2-mutant 1p/19q-codeleted oligodendrogliomas were rare and no molecular alterations significantly influenced survival, including MGMT-methylation status." (PMID 39164213, 2025). "Even glial tumors that are IDH1 R132H non-mutant but express ATRX, with IDH mutation assessed using molecular testing and 1p19q codeletion, are considered oligodendrogliomas." (PMID 39135755, 2024). "IDH1 R132H immunohistochemical and ATRX stains are now available at AKUH and at least two other laboratories in the country and will hopefully facilitate the diagnosis of oligodendroglioma." (PMID 38764578, 2024). "In Low-grade glioma (LGG) patients, including oligodendroglioma patients, overexpression of ISL2 was correlated with poor prognosis, and this correlation was not affected by gender or isocitrate dehydrogenase 1(IDH1) mutation status." (PMID 35965581, 2022). "We show differences in H3K27me3 staining between oligodendroglial and astrocytic lineages and between IDH1-R132H and non-canonical IDH1/2 Mut oligodendrogliomas." (PMID 34020723, 2021).